HNF1A (HNF1 homeobox A)
Diseases named in the same sentence as HNF1A in open-access papers (continued):
Sharing a sentence is not in itself a finding about the gene and the disease.
type 2 diabetes (continued). "Inactivating mutations in HNF1A and HNF4A causes congenital HH in children and then maturity-onset diabetes of youth (MODY type 3 in HNF1A and type 1 in HNF4A)." (PMID 28855921, 2017). "In this study, we screened 6 MODY genes (HNF4A, GCK, HNF1A, IPF1, HNF1B, and NEUROD1) for mutations in a Han Chinese family with suspected early-onset maternally inherited type 2 diabetes." (PMID 26981542, 2016). "Hepatocyte nuclear factor 1 alpha (HNF1A) controls many genes related to β-cell differentiation, and gene mutations are the most common cause of maturity-onset diabetes of the young." (PMID 26901059, 2016). "Heterozygous loss-of-function mutations in the hepatocyte nuclear factor 1α (HNF-1α) gene can lead to diminished amounts of functional HNF-1α, resulting in the onset of a particularly severe form of maturity-onset diabetes of the young (MODY)." (PMID 27551471, 2015). "One of the most common is the defect of the HNF1A (Hepatic Nuclear Factor 1A) gene, that accounts for approximately a half of all cases of maturity onset diabetes of the young (MODY)." (PMID 25987348, 2015). "Mutations in the transcription factor hepatocyte nuclear factor-1-alpha (HNF1A) result in the commonest type of maturity onset diabetes of the young (MODY)." (PMID 22808921, 2012). "A statistical interaction was observed between HNF1A G319S and baseline active cigarette smoking on the development of type 2 diabetes with similar adjustment (p = 0.006)." (PMID 21208426, 2011). "An interaction was present between the HNF1A G319S carrier status and active cigarette smoking at baseline on the outcome of incident type 2 diabetes (p = 0.006), with adjustment for age, sex, hypertension, triglyceride, and waist circumference." (PMID 21208426, 2011). "Nonetheless, the current study was able to retain a high 10-year follow-up rate of 89.1% and was able to investigate the prospective association between the population-specific genetic variation in HNF1A and incident type 2 diabetes." (PMID 21208426, 2011). "For instance, the early onset of type IIdiabetes referred to as MODY (maturity onset diabetes of the young) was mapped tomutations within the HNF1α (MODY3) andHNF4α (MODY1) gene." (PMID 19252740, 2009). "Importantly, HbA1c and fasting glucose PGSs were higher than in both type 2 diabetes and HNF1A-MODY groups, whereas type 2 diabetes PGS was lower." (PMID 41848901, 2026). "Similarly, transcripts of candidate genes for type 2 diabetes (Blk, C2cd4a, C2cd4b, Cdkn2a, Hnf1a, Mtnr1b, Pou5f1, Slc30a8) and type 1 diabetes (Cd69, Il2, IL27) were not expressed in the brain." (PMID 39920851, 2025). "In addition, a supra-additive effect of SU in combination with high concentrations of intravenous gastric inhibitory polypeptide (GIP) has also been shown in HNF1A maturity-onset diabetes of the young and in T2DM treated with standard dose glipizide." (PMID 38267622, 2024). "While the association of rare functionally damaging HNF1A variants with HNF1A-MODY and type 2 diabetes is well established owing to robust functional assays, the impact of HNF4A variants on HNF-4A transactivation in tissues including the liver and kidney is less known, due to lack of similar assays." (PMID 38433330, 2024). "Some mutations in HNF1A do not cause MODY but increase the susceptibility to type 2 diabetes and lower BMI." (PMID 37691384, 2023). "We did not observe any significant associations between HNF1A and type 2 diabetes or age of diagnosis in the population of African ancestry." (PMID 36216889, 2023). "No studies compared 1‐hour postprandial glucose of GCK‐MODY with HNF1A‐MODY/type 2 diabetes." (PMID 37226652, 2023). "In the future, studies that exert rigorous genetic standards for confirmation of genetic diabetes and report more results of basic adjunctive measurements like lipid metabolism are necessary to give further insight into the differences between GCK‐MODY and HNF1A‐MODY/type 2 diabetes." (PMID 37226652, 2023).
type 2 diabetes (continued). "In support of other recent studies, we note surprisingly low penetrance rates for GCK (77% of PTV carriers with T2D) and HNF1A (48%) for effects that are clinically considered to be highly/completely penetrant for monogenic forms of maturity-onset diabetes of the young (MODY)." (PMID 36530175, 2022). "Individuals with HNF1A-MODY are leaner than individuals with type 2 diabetes." (PMID 34951657, 2022). "Even though the patients had distinct biochemical pathways affected, it was not possible to find any urinary biomarkers which could distinguish patients with GCK-MODY and HNF1A-MODY from patients with type 2 diabetes." (PMID 35179657, 2022). "In addition, certain HLA alleles associated with T1D and common polymorphism of the maturity-onset diabetes of the young (MODY) genes, such as GCK (MODY2 gene) and HNF1A (MODY3 gene), have been reported to associate with GDM." (PMID 36432486, 2022). "Mutations in the HNF4A and HNF1A genes are the cause of the most frequent type of types 1 and 3 maturity-onset diabetes of the young (HNF1A-MODY), respectively and also represent a risk for type 2 diabetes, metabolic syndrome, coronary heart disease, pancreas and liver cancer and ulcerative colitis." (PMID 35741825, 2022). "HNF1A and HNF4A are established genes causing maturity-onset diabetes of the young (MODY)." (PMID 34362956, 2021). "At HNF1A, some common and rare signals have been associated with low-density lipoprotein (LDL) cholesterol, circulating C-reactive protein levels, and risk of monogenic diabetes (maturity-onset diabetes of the young type 3) or multi-factorial T2D29–31." (PMID 33531528, 2021). "Variants in other interaction partners of NCOA3 including insulin growth factor 1 (IGF1 rs5742643), HNF1 homeobox A (HNF1A rs1800574 and rs56348580), and IQ motif containing K (IQCK rs7185636) were associated with systolic blood pressure, type 2 diabetes, or Alzheimer’s disease, respectively." (PMID 34864818, 2021). "Our previous publication demonstrated that 1,5-AG may distinguish HNF1A MODY from type 2 diabetes within HbA1c range 6.5–9.0%." (PMID 30778899, 2019). "However, HNF1α is involved in many other metabolic pathways with relevance for monogenic or polygenic type 2 diabetes." (PMID 28493909, 2017). "Although in cases with occurrence of type 2 diabetes and HNF1A-MODY-relevant mutations such as this, treatment of type 2 diabetes is the major clinical aim, therapy should be optimized according to the patients’ genetic profile because a MODY-relevant mutation alters the therapeutic needs." (PMID 27142837, 2016). "HNF1A, which encodes the transcription factor hepatocyte nuclear factor (HNF)-1a, also suggests a common pathogenic background, as previous GWA studies have identified associations with atherogenic dyslipidemia, vascular inflammation, and type 2 diabetes." (PMID 22022282, 2011). "Mutations in HNF1A can cause a variety of protein malfunctions, ranging from severe loss-of-function (LOF) variants connected to highly penetrant MODY to milder LOF variants with lower penetrance, yet increasing the risk of type 2 diabetes in the population by up to fivefold." (PMID 40018479, 2025). "In conclusion, we have shown that biologically important functional variants, specifically those within the functional domains of HNF1A, are associated with type 2 diabetes in populations of European ancestry, but not in those of African or Hispanic-Latino ancestry." (PMID 36216889, 2023). "Therefore we tested the role of HNF1a, one of maturity onset diabetes of the young (MODY) genes." (PMID 34843575, 2021). "This represents ∼23% and ∼26% of total HNF1A missense variants in the UK and Norway MODY registries, respectively, that overlap with the functionally interrogated HNF1A missense variants detected in the exomes of ∼13K multi-ethnic type 2 diabetes cases and controls." (PMID 32910913, 2020).
type 2 diabetes (continued). "Therefore it is tempting to speculate that HNF1A-MODY is under-diagnosed in the ‘sink’ of common type 2 diabetes." (PMID 27142837, 2016). "There were 23 and 14 articles that compared GCK‐MODY with HNF1A‐MODY (HNF1A‐MODY studies) and type 2 diabetes (type 2 diabetes studies), respectively." (PMID 37226652, 2023). "In summary, this study is the first worldwide meta‐analysis to explore the differences in basic clinical results between GCK‐MODY, HNF1A‐MODY, and type 2 diabetes." (PMID 37226652, 2023). "The pathway analysis showed that HNF1A and TCF7L2 genes were responsible for maturity-onset diabetes of the young (MODY) and human papillomavirus infection and prostate cancer pathways, respectively." (PMID 38096208, 2023). "Only one study compared 2‐hour C‐peptide (2‐h CP) between GCK‐MODY and HNF1A‐MODY (SMD 0.44 [95% CI 0.05, 0.83] nmol/l, p = .03, n = 1)/type 2 diabetes (SMD −0.71 [95% CI −1.01, −0.41] nmol/l, p < .001, n = 1) patients." (PMID 37226652, 2023). "Male patients accounted for 43.99%, 41.08%, and 44.82% in GCK‐MODY, HNF1A‐MODY, and type 2 diabetes, respectively." (PMID 37226652, 2023). "For Δ2‐h PG, GCK‐MODY patients also had a lower Δ2‐h PG compared to both HNF1A‐MODY (SMD −1.49 [95% CI −1.98, −1.01] mmol/l, p < .001, n = 3; I2 = 0%, Ph = .37) and type 2 diabetes (SMD −1.02 [95% CI −1.32, −0.71] mmol/l, p < .001, n = 1) as well." (PMID 37226652, 2023). "In HNF1A-MODY the frequency of cardiovascular and microvascular complications is high and similar to that of patients with type 1 and type 2 diabetes." (PMID 32528556, 2020). "Accuracy of hsCRP to distinguish between HNF1A-MODY patients and young adult- onset type 2 diabetes, as measured by ROC-derived C-statistic, ranged from 0.79 to 0.91, depending on the center." (PMID 32528556, 2020). "Serum concentration of 1,5-AG was the lowest in type 1 diabetes group, followed by HNF1A MODY and type 2 diabetes patients." (PMID 30778899, 2019). "Concentration of hsCRP was lowest in HNF1A MODY (0.51 mg/l) and highest in type 2 diabetes (1.33 mg/l)." (PMID 30778899, 2019). "It was significantly lower in type 2 diabetes group (p < 0.001 vs. GCK MODY), and the lowest in type 1 diabetes and HNF1A MODY patients (p < 0.001 and p = 0.017, respectively vs. type 2 diabetes)." (PMID 30778899, 2019). "Hypoglycaemia, hyperinsulinaemic (C1864903) and Diabetes, type 2 (C0011860) were connected through the genes HNF1A, ABCC8, HNF4A, and GCK, as well as the KEGG pathway Type II Diabetes Mellitus." (PMID 30255817, 2018). "We aimed to assess the response to a single dose of 10 mg dapagliflozin in patients with Hepatocyte Nuclear Factor 1 Alpha (HNF1A)-MODY, Glucokinase (GCK)-MODY, and type 2 diabetes." (PMID 28593615, 2017). "In a randomised trial sulfonylureas led to a fourfold greater reduction of fasting blood glucose in HNF1A-MODY patients compared with age, BMI and blood glucose level-matched type 2 diabetes patients." (PMID 28314945, 2017). "It appears that there are differences in the gut microbiome composition between patients with HNF1A-MODY and type 2 diabetes." (PMID 27807544, 2016). "In conclusion, it appears that there are differences in gut microbiome composition between patients with HNF1A-MODY, control individuals, and patients with type 2 diabetes." (PMID 27807544, 2016). "Moreover, mir-24 has also been found to inhibit β-cell proliferation and insulin secretion by targeting maturity-onset diabetes of the young (MODY) genes, Hnf1α and Neurod1." (PMID 41384367, 2026). "The pooled SMD for HNF1A‐MODY studies was −0.71 (95% CI −2.50, 1.08) (p = .44, n = 5; I2 = 98%, Ph <.01) and was −11.79 (95% CI −31.68, 8.11) (p = .25, n = 3; I2 = 100%, Ph <.01) for type 2 diabetes studies." (PMID 37226652, 2023).
type 2 diabetes (continued). "GCK‐MODY patients were younger on average than those with HNF1A‐MODY (SMD −0.39 [95% CI −0.71, −0.07] years, p = .02, n = 17; I2 = 84%, Ph <.01) or type 2 diabetes (SMD −2.26 [95% CI −4.01, −0.51] years, p = .01, n = 12; I2 = 99%, Ph <.01) at the time of diagnosis." (PMID 37226652, 2023). "However, GCK‐MODY patients had lower 2‐h PG compared to both HNF1A‐MODY (SMD −1.60 [95% CI −2.44, −0.76] mmol/l, p < .001, n = 5; I2 = 82%, Ph <.01) and type 2 diabetes patients (SMD −1.06 [95% CI −1.65, −0.47] mmol/l, p < .001, n = 2; I2 = 90%, Ph <.01)." (PMID 37226652, 2023). "The utility of routine biochemical biomarkers such as hsCRP or antibodies have been investigated for distinguishing several genetic etiologies (HNF1A, HNF4A, HNF1B) from Type 1 or Type 2 diabetes, or for distinguishing HNF1A specifically from Type 2 diabetes using HDL-cholesterol or hsCRP64–69." (PMID 37794142, 2023). "In another British study, a cutoff point of 0.75 mg/L had a positive predictive value (PPV) of 2.7% and a negative predictive value (NPV) of 99.7% when comparing HNF1A-MODY to type 2 diabetes." (PMID 32528556, 2020). "Its serum level was lower in HNF1A MODY when compared with GCK MODY, type 1, and type 2 diabetes." (PMID 30778899, 2019). "Our prediction identified the m6A genes HNF1B, HNF1A, WFS1, and IRS2 as the potential disease genes, which could provide a new clue to study the role of m6A in type 2 diabetes." (PMID 30601803, 2019). "We examined 14 HNF1A-MODY, 19 GCK-MODY, and 12 type 2 diabetes patients." (PMID 28593615, 2017). "Plasma levels of apoM were also decreased in maturity-onset diabetes of the young (MODY3) subjects, might attribute to the hepatocyte nuclear factor-1α (HNF-1α)-dependent impairment of apoM expression leaded by heterozygous HNF-1α mutations." (PMID 27576735, 2016). "We have previously reported a higher prevalence of type 2 diabetes among HNF1A S319 carriers compared to non-carriers in this population, which is paradoxical in the context of the current finding of S319 carriers having a low level of CRP." (PMID 20716378, 2010). "Furthermore, some recent studies (comparing HNF1A-MODY to young-onset type 2 diabetes) challenged this paradigm, indicating that hsCRP does not improve diagnosis." (PMID 30013516, 2018). "Systems biology approaches identified HNF1A, PDX1 and REST as drivers of gene co-expression modules correlated with impaired insulin secretion or glucose tolerance, and 14 out of 19 differentially expressed type 2 diabetic islet signature genes were enriched in these modules." (PMID 29185012, 2018). "We observed no statistical differences for fasting insulin (HNF1A‐MODY studies: SMD 0.18 [95% CI −0.21, 0.58] mIU/l, p = .36, n = 6; I2 = 66%, Ph = .01; type 2 diabetes studies: SMD −0.60 [95% CI −1.24, 0.04] mIU/l, p = .07, n = 3; I2 = 77%, Ph = .01)." (PMID 37226652, 2023). "We initially examined 51 HNF1A-MODY patients, 56 subjects with type 1 diabetes (T1DM), 39 with type 2 diabetes (T2DM) and 43 non-diabetic individuals (ND) from Poland." (PMID 22350134, 2013). "Furthermore, the BMI Z‐score results showed that for pediatric patients who almost met MODY criteria, patients with GCK‐MODY, HNF1A‐MODY, or type 2 diabetes did not have not a statistically significant difference in growth stages." (PMID 37226652, 2023). "For HDL however, this adjunctive examination is not helpful in distinguishing GCK‐MODY from HNF1A‐MODY, but its difference may be helpful in distinguishing GCK‐MODY from type 2 diabetes." (PMID 37226652, 2023). "After adjusting for confounders, the level of hsCRP remained lower in HNF1A MODY than in GCK MODY (p = 0.033) or in type 1 diabetes (p = 0.018), wheseas the adjusted difference between type 2 diabetes and HNF1A MODY was not significant, although it remained numerically large (0.5 mg/l, p = 0.45)." (PMID 30778899, 2019).
type 2 diabetes (continued). "We aimed to investigate gut hormones, lipids, and insulin regulation in response to a meal test in HNF1α defect carriers (MODY3) compared to non-diabetic subjects (controls) and type 2 diabetes (T2D)." (PMID 28493909, 2017).
Hyperglycemia (55 papers, 2004 to 2025). An increased concentration of glucose in the blood. "In our study, the HNF1A:c.1136_1137del (p.Pro379fs) variant in Family 105 was associated with progressive hyperglycemia, consistent with the characteristic phenotype of HNF1A‐MODY." (PMID 41497485, 2025). "The most common subtypes of MD are caused by pathogenic variants in GCK (GCK-hyperglycemia) or HNF1A (HNF1A-MD) genes." (PMID 41409604, 2025). "To avoid the interference of hyperglycemia and diabetic phenotype on the metabolic functions and pathways readouts, we decided to use mice heterozygous for Hnf1a mutation." (PMID 38825059, 2024). "Clinically, patients with HNF1A mutations will manifest glucose intolerance during adolescence or early adulthood with progressive hyperglycemia, and low renal glucose threshold." (PMID 39420387, 2024). "By contrast, HNF1A‐MODY involves obvious hyperglycemia and a high predisposition to diabetic vascular complications, but it responds well to sulfonylurea hypoglycemic agents." (PMID 37226652, 2023). "We then explore the mechanism of hyperglycemia caused by HNF1α mutation by discussing the role of HNF1α in the islets and liver." (PMID 35299962, 2022). "We firstly generated a similar variant in zebrafish (hnf1a+/−), and the animal displayed hyperglycemia, which was a diabetic phenomenon." (PMID 36361808, 2022). "Patients with hyperglycemia caused by HNF1A variant can remain sulfonylurea responsive for many years." (PMID 35592779, 2022). "As far as the optimal treatment of gestational hyperglycemia is concerned, insulin is necessary if only the mother carries an HNF1A mutation." (PMID 35052457, 2022). "Patients with HNF1A heterozygous mutations show β cell dysfunction and hyperglycemia due to insufficient insulin release in response to increased blood glucose levels." (PMID 34295307, 2021). "In particular, in ABCC8 gene mutations, hyperglycemia generally starts in adolescence, while in HNF1α/4α in prepubertal age." (PMID 32928245, 2020). "As a consequence, carriers of HNF1A mutations show glycosuria that begins several years before hyperglycemia and is likely due to down regulation of SLC5A2 which encodes SGLT2, a sodium-dependent glucose transporter known to play a major role in renal glucose reabsorption." (PMID 35052457, 2022). "The dysfunction of mature β cells is the main reason for the hyperglycemia caused by HNF1α." (PMID 35299962, 2022). "However, it remains poorly understood whether renal dysfunction in MODY3 patients occurs primarily due to prolonged exposure to hyperglycemia or the direct effects of HNF1A mutation contributing to renal dysfunction." (PMID 37137894, 2023). "Mean fasting glucose was significantly higher in GCK-hyperglycemia in the first trimester when compared to the HNF1A-MD group." (PMID 41409604, 2025). "This study evaluates clinical management and pregnancy outcomes in GCK-hyperglycemia and HNF1A-MD pregnancies focusing on insulin therapy, glycemic control and neonatal outcomes." (PMID 41409604, 2025). "In conclusion, maternal and neonatal outcomes in pregnancies affected by GCK-hyperglycemia and HNF1A-MD were largely favorable and comparable between groups." (PMID 41409604, 2025). "The rates of caesarean deliveries in subtypes of GCK-hyperglycemia and in HNF1A-MD were similarly high." (PMID 41409604, 2025). "We analyzed 36 pregnancies from 27 patients: 18 pregnancies occurred in the context of 14 patients with GCK-hyperglycemia, and 18 pregnancies in 13 patients with HNF1A-MD." (PMID 41409604, 2025). "GCK-hyperglycemia patients received a higher total daily dose of insulin during the first trimester than HNF1A-MD patients (0.54 ± 0.14 vs. 0.41 ± 0.17 units/kg, p=0.041)." (PMID 41409604, 2025). "This study provides a detailed comparison of pregnancies affected by GCK-hyperglycemia and HNF1A-MD." (PMID 41409604, 2025). "The incidence of macrosomia — 20% GCK-hyperglycemia and 11.1% in HNF1A-MD—was lower than previously reported in both subtypes." (PMID 41409604, 2025).